IL1B (interleukin 1 beta)
Diseases named in the same sentence as IL1B in open-access papers (continued):
Sharing a sentence is not in itself a finding about the gene and the disease.
liver fibrosis (continued). "Age-related declines in SIRT1 activity trigger inflammatory pathways such as NOD-like receptor protein 3 (NLRP3) and Interleukin-1 beta (IL-1β), exacerbating liver fibrosis." (PMID 40052151, 2025). "Excessive activation of NLRP3 inflammasomes in mice can lead to hepatocyte pyroptosis and cause severe liver inflammation and fibrosis, and pyroptosis products IL-1β and IL-18 regulate the activation of HSCs and promote liver fibrosis in vitro." (PMID 40667485, 2025). "IL-17A has been shown to stimulate the activation of HSCs and contribute to liver fibrosis by increasing the expression of pro-inflammatory cytokines, such as IL-6, IL-1β, and TNF-α, as well as pro-fibrotic factors like TGF-β and α-SMA." (PMID 39995661, 2025). "Collectively, these studies highlight the therapeutic potential of targeting IL-1β in liver fibrosis." (PMID 39995661, 2025). "Further research found that the increased CRP, IL-1β, and TNF-α were significantly associated with MASH and hepatic fibrosis." (PMID 39605886, 2024). "The serum level of IL-1B shows an elevation in the case of hepatitis, cirrhosis, liver fibrosis and HCC." (PMID 38553531, 2024). "On the other hand, there is also an aspect that enhances the production of proinflammatory cytokines such as TNF-α and IL-1β, worsening liver fibrosis." (PMID 39316687, 2024). "Our current study confirmed the anti-inflammatory effects of vitamin D supplementation on mice with liver fibrosis through reductions in IL-1β, IL-4, IL-6, and TNFα in addition to OPN." (PMID 39654627, 2024). "Because inflammatory cytokines play crucial roles in the development and progression of hepatic fibrosis, we quantified IL-1β, IL-6, and TNF-α levels using ELISA kits." (PMID 38434258, 2024). "Studies have shown that TAA-induced liver fibrosis can be ameliorated by inhibiting IL-1β recruitment and secretion by monocytes/macrophages." (PMID 39519763, 2024). "In the LPS-activated liver fibrosis cell model, the content of IL-1β increased by 20% compared with the normal group, indicating an increase in inflammation." (PMID 38576476, 2024). "While, multivariate logistic regression analysis revealed that low mean relative gene expression level of IL-1β (p value < 0.001), and high NFS (p = 0.021) significantly associated with hepatic fibrosis in MAFLD patients as presented in." (PMID 39179677, 2024). "Remarkably, the liver fibrosis mice treated with vitamin D resulted in a substantial reduction in the levels of the tested cytokines: IL-1β (2.2-fold), IL-4 (1.9-fold), IL-6 (8-fold), OPN (1.45-fold), and TNF-α (1.7-fold) compared to CCl4 alone." (PMID 39654627, 2024). "Pearson's correlation analysis showed that post-MAFLD hepatic fibrosis positively correlated with low expression levels of IL-1β, low expression levels of NLRP3, and high NFS values." (PMID 39179677, 2024). "Patients with liver fibrosis showed higher IL-1β expression in the liver, indicating high levels of liver inflammation in patients with hepatic fibrosis." (PMID 38172440, 2024). "We identified the NLRP3/Cleaved Caspase-1/IL-1β signaling in the liver to evaluate the impact of MP-40 on hepatic fibrosis and to clarify the mechanism of action of MP-40 in treating hepatic fibrosis." (PMID 39372196, 2024). "The same trend was observed in male Gpr183–/– compared to male WT with significantly lower levels of pro-inflammatory marker Il1β, liver fibrosis markers α-SMA, Col1a1, and Mcp1, and macrophage markers Adgre1 and Cd14." (PMID 39545055, 2024). "Inhibiting ACOX1 expression effectively improves steatohepatitis and liver fibrosis and inhibits the IL-1β and α-SMA pathways." (PMID 38595921, 2024). "MT was demonstrated to produce an antioxidant influence protecting the hepatocytes from free radical injury and inhibiting pro-inflammatory cytokines such as TNF-α and IL-1β, retarding the development of liver fibrosis." (PMID 38540717, 2024).
liver fibrosis (continued). "AA did not exert the anti‐inflammatory effect as reported in rats with CCl4‐induced liver fibrosis that AA significantly reduced hepatic mRNA expression of Il1b, Il6, and Tnfa." (PMID 39501714, 2024). "Overall, our findings suggested that SWT restored liver sinusoidal permeability and alleviated the progression of liver fibrosis by inhibiting COL8A1/IL-1β/OLR1 conducted LSEC angiogenesis, adhesion and defenestration." (PMID 39741334, 2024). "In the current study, we compared the expression levels of NLRP3 and IL-1β in MAFLD individuals with varying degrees of hepatic fibrosis and steatosis and found a considerable lowering in their expression levels was linked to advanced fibrosis." (PMID 39179677, 2024). "This subsequently increases expression of fibrogenic and inflammatory proteins (e.g., α-SMA and IL-1β), exacerbating liver fibrosis." (PMID 39105051, 2024). "After suffering from liver fibrosis, the levels of IL-1β and IL-6 in the liver were significantly increased (p < 0.001 vs. control group)." (PMID 39195542, 2024). "We established that suppressed hepatic sympathetic nerve activity in HIRI caused by Bmal1 downregulation in the CG resulted in decreased liver fibrosis and inflammatory cytokine levels, including IL-1β and TNF-α." (PMID 37189459, 2023). "Recent research has shown that as hepatic fibrosis progresses, macrophages induce the expression of IL-1β/IL-18." (PMID 36834849, 2023). "Serum TNF-α, IL-1β, and IL-6 concentrations in mice with CCl4-induced liver fibrosis were increased in our study, which coincided with the assay results of inflammatory factors in previous studies." (PMID 38116381, 2023). "Similar to our previous results in CCl4-induced hepatic fibrosis, the expression of inflammatory factors IL1β and TNFα was significantly decreased in the livers of myeloid-specific RBP-J knockout mice with NAFLD in this study." (PMID 37063432, 2023). "Second, TNF-α/IL-1β pretreatment enhanced the efficacy of hADSCs in the improvement in hepatic function and liver fibrosis in BDL mice and increased the ability of hADSCs to inhibit HSC activation." (PMID 37095581, 2023). "Meanwhile, TGF-β can synergize with IL-6, TNF-α, or IL-1β to accelerate the development of hepatic fibrosis." (PMID 38074148, 2023). "Consistent with the marked reduction of hepatic fibrosis by gemigliptin, TNFα and IL1B were significantly lower in the liver and plasma of the gemigliptin-treated group than in the MCD diet–fed group." (PMID 37739179, 2023). "The activation of the NLRP3 inflammasome, on the one hand, produces IL-1β and IL-18, leading to liver fibrosis." (PMID 36900523, 2023). "Mechanistically, deletion of SIRT1 in hepatocytes resulted in NLRP3 and IL‐1β induction, pro‐inflammatory response, and severe liver fibrosis in young mice, mimicking the ability of aging to impair the resolution of established fibrosis." (PMID 36999514, 2023). "TNF-α and IL-1β activated by macrophage-induced signals contribute to hepatocellular death, promote inflammatory cell recruitment, activate HSCs, and accelerate hepatic fibrosis." (PMID 36834849, 2023). "First, NLRP3 inhibition by MCC950 effectively suppresses IL‐1β expression, inflammatory cell infiltration, and liver fibrosis in alcohol‐fed old mice." (PMID 36999514, 2023). "The gene expression levels of TNF‐α, IL‐1β and IL‐6 are concomitantly increased, and one such inflammatory reaction has been suggested to play a major contribution to hepatic fibrosis and disruption of lipid metabolism." (PMID 37177862, 2023). "The induction of IL‐1β was further amplified by threefold in SIRT1 LKO mice, suggesting the presence of NLRP3+ cells and elevation of IL‐1β as key pathological features of liver fibrosis associated with SIRT1 loss." (PMID 36999514, 2023). "Liu and colleagues found that liver expression of GSDMD, NLRP3, caspase-1 and IL-1β increased in Schistosoma japonicum-infected mice, leading to exacerbation of hepatic fibrosis." (PMID 38086792, 2023).
liver fibrosis (continued). "A number of studies have demonstrated that IL-6 and IL-1β play a crucial role in the progression of steatosis to steatohepatitis and liver fibrosis." (PMID 37504922, 2023). "The results showed that FA inhibited the proliferation and migration of LX2 cells and adjusted the expression of MMP-1, TIMP-1, COLI, α-SMA, TNF-α, IL-6 and IL-1β as well as promoted collagen metabolism to show potential in anti-hepatic fibrosis." (PMID 35035671, 2022). "For different subtypes of NAFLD, we found significant associations of CRP, IL-1β, and TNF-α with NASH and hepatic fibrosis." (PMID 35603224, 2022). "Under long‐term inflammatory stimulation, IL‐1β can recruit immune cells such as monocytes, macrophages and dendritic cells into the liver, which interact with HSCs to promote the progression of liver fibrosis." (PMID 35415891, 2022). "Our results also showed that CRP, IL-1β, and TNF-α were significantly associated with non-alcoholic steatohepatitis (NASH) and hepatic fibrosis." (PMID 35603224, 2022). "It has been demonstrated that tlr-9 knockout mice with a choline-deficient L-amino acid-defined (CDAA) diet are protected against lipid accumulation, steatohepatitis, and liver fibrosis through suppressing IL-1β production." (PMID 35165344, 2022). "Here, augmented levels of pyroptosis-related indicators GSDMD, IL-1β, and IL-18 were verified in both liver fibrosis patients and CCl4-induced fibrotic mouse model." (PMID 36429008, 2022). "Malvidin was found to reduce the development of liver fibrosis by inducing hepatic stellate cell apoptosis and to inhibit TNFα and interleukin (IL)-1β secretion from activated macrophages." (PMID 36232316, 2022). "IL-1β plays a major role in the progression of steatosis to steatohepatitis and liver fibrosis, and levels were decreased at mRNA and protein levels, although not significantly." (PMID 35349482, 2022). "By inhibiting the expression of IL-1B in a mouse model, the numbers of macrophages and neutrophils in the liver were reduced, and liver fibrosis was improved." (PMID 36380355, 2022). "IL-1β, a potent inflammatory cytokine, promotes hepatic stellate cell proliferation and is involved in the pathogenesis of hepatic fibrosis, the latter of which can be induced by several factors, such as toxins, ethanol, and NASH." (PMID 35614939, 2022). "qPCR analysis showed that the expression of Tgf-β1, which promotes liver fibrosis, was lower in p62-mRes mice, but the expression of other markers of inflammation (Tnfa and Il-1β) and fibrosis (Col1a1) were unaffected." (PMID 36439272, 2022). "Previous research found that macrophages secreted IL-1β and IL-6, which promoted hepatocyte injury and liver fibrosis." (PMID 35603224, 2022). "Here, elevated levels of the pyroptosis-related indicators GSDMD, IL-1β, and IL-18 were confirmed in both clinical specimens from liver fibrosis patients and CCl4-induced liver fibrosis mouse models." (PMID 36429008, 2022). "Immunohistochemical (IHC) analysis revealed that the expression of hepatic GSDMD, IL-1β, and IL-18 was significantly upregulated in patients with liver fibrosis compared to HCs." (PMID 36429008, 2022). "We also measured hepatic expression of genes involved in detoxification/drug metabolism (Cyp1a1, Cyp1b1), inflammation (Il1b) and hepatic fibrosis (Col1a1)." (PMID 35788891, 2022). "According to an earlier study, macrophages release IL-1β, which increases hepatocyte damage and liver fibrosis." (PMID 36297117, 2022). "The levels of TNF-α, IL-1β, phospho-p65 and other NF-κB signalling markers were increased in the progression of liver fibrosis." (PMID 33691755, 2021). "Among them, NF-κB induces the expression of pro-inflammatory cytokines, such as TNF-α and IL-1β, which produces the cytotoxic environment, thereby further triggering the development of chronic inflammation and progressive liver fibrosis." (PMID 34867416, 2021).
liver fibrosis (continued). "In our study, SNS treatment reduced the serum and liver contents of TNF-α, IL-1β as well as IFN-γ in mice with liver fibrosis." (PMID 34276360, 2021). "IL-1β produced by macrophages recruit the inflammatory factors to the liver and activate hepatic stellate cells, thereby developing liver fibrosis." (PMID 34722615, 2021). "IL-1β can also promote hepatocyte apoptosis and aggravate liver fibrosis by activating NF-κB in HSCs." (PMID 34956171, 2021). "The levels of the NF-ΚB signalling pathway activation markers TNF-α, IL-1β and phospho-p65 were increased by CssPLA2 in the context of liver fibrosis." (PMID 33691755, 2021). "Following induction of liver injury by CCl4 or other stimulators, a variety of cells generate proinflammatory cytokines, including TNF-α and IL-1β, to promote liver fibrosis." (PMID 34276360, 2021). "Pradere and colleagues confirmed that TNF-α and IL-1β accelerated liver fibrosis by promoting the survival of activated HSCs in vitro and in vivo." (PMID 33117360, 2020). "Based on results of network pharmacology, it was known that flavonoids can possibly suppress liver fibrosis by inhibiting the IL-17 signaling pathway, which includes NF-κB, AP-1, IL-6, IL-1β, TNFα, IFN-γ, CCL2, COX2, MMP1, MMP3, and MMP9." (PMID 33551818, 2020). "Nevertheless, NLRP3 inflammasome acts indirectly on the adaptative immune system by stimulating caspase-1 and IL-1β production, which favor Th17 cell differentiation and secretion of IL-17, resulting in continuous liver fibrosis state." (PMID 32085494, 2020). "IL-1α and IL-1β act synergistically in promoting development of liver fibrosis, as shown in a study that blocking the expression of either of them in vivo was sufficient to protect mice from developing steatohepatitis." (PMID 32085494, 2020). "In both models, IL-1β was upregulated upon liver fibrosis induction in the liver (2–5-fold) and serum (4–6-fold)." (PMID 30875826, 2019). "In both models, liver IL-1β mRNA expression levels were significantly upregulated in all mice groups following liver fibrosis induction." (PMID 30875826, 2019). "In particular, the role of IL-1β and its receptor (IL-1R) targeting agents in renal and hepatic fibrosis has been evaluated in a few animal model studies." (PMID 30616602, 2019). "In the microenvironment of liver fibrosis, secreted IL-1β and TNF-α have been shown to promote the survival of activated HSCs and increase the inflammation reaction." (PMID 28871223, 2017). "The mRNA levels of Tnf and Il1b significantly increased after Sj infection at week 6 during acute liver fibrosis and subsequently remained high at the advanced liver fibrosis stage (week 8)." (PMID 29321784, 2017). "TLR9, which is activated by bacterial DNA, is also required for liver fibrosis through the induction of IL-1β, which in turn activates the IL-1 receptor on HSCs, resulting in their activation." (PMID 28761060, 2017). "As a key inflammatory mediator upstream of IL-6 and TNF-α signaling cascades, IL-1β is produced primarily by activated macrophages and has been demonstrated to be involved in diverse acute and chronic liver injury, including liver fibrosis." (PMID 27924062, 2016). "IL-1α or IL-1β knock-out mice are also less likely to develop liver fibrosis in animal models of steatohepatitis." (PMID 27046197, 2016). "In this work we observed a strong anti-inflammatory effect of Omegaven® on human monocytes activated by LPS, nearly suppressing IL-6, IL-8, IL-1β and TNFα whose elevated levels have been associated previously with NASH and liver fibrosis." (PMID 25502575, 2014). "Profibrotic factors such as IL-1α and IL-1β that play a role in liver fibrosis development, and TNF-α which is an essential cofactor of IL-13 to induce the expression of IL-13Rα2, were upregulated." (PMID 24143891, 2013).
liver fibrosis (continued). "The identification of the Hepatic Fibrosis/Hepatic Stellate Cell Activation pathway (identified by Vegfa, Il1a, Tgfb1, Tgfa, Il1b, and Pgf) is interesting, as the polarization of M2 macrophages is a critical component of this pathology." (PMID 24156623, 2013). "IL-1β levels were significantly higher in individuals with chronic hepatitis C and revealed a possible linkage of increasing IL-1β with liver fibrosis, suggesting involvement of IL-1β with HCV disease." (PMID 23633957, 2013). "Interleukin 1β (IL-1β), produced by macrophages, enhances hepatic inflammation by recruiting myeloid cells and activating HSCs, thereby promoting increased collagen production and facilitating liver fibrosis development." (PMID 40249927, 2025). "Currently, IL-1β is being explored as a potential therapeutic target for liver fibrosis." (PMID 39995661, 2025). "This review highlights a significant increase in infiltrating monocytes in diabetic livers, with hepatic macrophages shifting to a pro-inflammatory state, elevating IFN-γ, TNF-α, IL-1β, IL-15, and IL-18, promoting inflammation, and contributing to liver fibrosis." (PMID 40362271, 2025). "IL-1β can stimulate the inflammatory response in the liver and activate HSCs by recruiting myeloid cells, promoting collagen production and the development of liver fibrosis." (PMID 40249927, 2025). "Furthermore, the injection of SVF via the portal vein significantly reduced thioacetamide-induced liver fibrosis, with lower mRNA levels of IL-1β, IL-6, and TNF-α compared to the ASC and PBS-injected groups." (PMID 40547297, 2025). "According to reports, TLR4 can promote the production of inflammatory factors (such as TNF-α and IL-1β) and affect the activation of hepatic stellate cells, thus exacerbating liver fibrosis and inflammatory reactions in alcohol-induced liver injury by activating Kupffer cells." (PMID 39861457, 2025). "IL-1β, a potent pro-inflammatory cytokine, exerts a pro-inflammatory role through interaction with the interleukin-1 receptor (IL-1R1) in an autocrine or paracrine manner, thereby driving the occurrence of liver fibrosis." (PMID 39635524, 2024). "Moreover, pretreatment with NLRP3 knockdown reversed the upregulation of proteins associated with the NLRP3 inflammasome and liver fibrosis induced by GCDCA in LPS-primed LX2 cells, and IL-1β secretion was also reduced." (PMID 38172440, 2024). "Patients with post-MAFLD hepatic fibrosis had significantly higher relative gene expression levels of IL-1β and NLRP3; with IL-1β > 1.1 had AUC of 0.919, sensitivity of 88.33, specificity of 96.26, PPV of 96.4, and NPV of 88 and 92.3 accuracy (p value < 0.001)." (PMID 39179677, 2024). "The present study provides novel evidence for the possible involvement of IL-1β and NLRP3 inflammasome in metabolic-associated fatty liver disease pathogenesis and could be valid markers for the early detection of post-MAFLD hepatic fibrosis." (PMID 39179677, 2024). "Additionally, SWT disrupted the intercellular crosstalk between LSECs and hepatic stellate cells (HSCs) driven by IL-1β, thus alleviating liver fibrosis." (PMID 39741334, 2024). "In summary, IL-1β of LSECs could activate HSCs through a paracrine pathway to promote hepatic fibrosis, while SWT significantly reversing this process." (PMID 39741334, 2024). "Inhibition of IL-1β has been shown to improve steatohepatitis and liver fibrosis in animal models." (PMID 38595921, 2024). "In addition, rats with lower IL-1β levels exhibited a significant reduction in the transition from steatosis to steatohepatitis and liver fibrosis, suggesting that IL-1β also plays a key role in liver injury." (PMID 37547679, 2023). "Research shows that when HSC are stimulated by mediators released from blast cells or inflammatory cells, inflammasome induce pyroptosis by activating caspase-1 and releasing pro-inflammatory factors IL-1β and IL-18, which in turn drive the progression of liver fibrosis." (PMID 37081882, 2023).